IL6 (interleukin 6)
Diseases named in the same sentence as IL6 in open-access papers (continued):
Sharing a sentence is not in itself a finding about the gene and the disease.
lymphopenia (continued). "This is biologically plausible, as neutrophils and monocytes produce cytokines such as IL-1, IL-6, and TNF-α, which stimulate osteoclastogenesis, while lymphopenia may reflect diminished osteoprotective T-cell activity." (PMID 41140653, 2025). "Hematological changes, including lymphopenia, eosinopenia, and neutrophilia, alongside increased NLR, CRP, IL-6, ferritin, and D-dimer levels, have been consistently associated with disease prognosis and mortality in SARS-CoV-2 infection across various geographical regions." (PMID 41472264, 2025). "Some studies suggest a potential link between lymphopenia and elevated levels of IL‐10, TNF or IL‐6, which may act directly on lymphocytes or indirectly via other cell lineages (e.g. neutrophils and DCs)." (PMID 41163794, 2025). "In addition, both ICU and ward patients had pronounced lymphopenia, increased D-dimer, ferritin, hs-CRP, IL-6 levels, and LDH activity." (PMID 37629114, 2023). "Laboratory data: initial blood work revealed a high WBC (White Blood Cells) in 50,9%, lymphopenia in 88,48%, high CRP and IL-6 levels in 100% and 90,9% respectively, hyperferritinemia in 91,5%, as well as high d-dimers and fibrinogen levels in 98,7% and 87,8% respectively." (PMID 38007416, 2023). "In the SI group, the statistically significant IL-6 decrease in the early inflammatory phase coincided with normalization of their initial lymphopenia, in contrast to the CI group." (PMID 37147677, 2023). "The presence of lymphopenia in the context of AMI is secondary to the increased production of cortisol and elevated degree of lymphocyte apoptosis, further resulting in the secretion of proinflammatory indicators including TNF-αand IL-6." (PMID 36474135, 2022). "Muscle-derived IL-6, one of the myokines with anti-inflammatory properties, inhibits TNF production and stimulates the production of IL-1ra and IL-10 as well as cortisol production, leading to lymphopenia and neutrocytosis." (PMID 36077525, 2022). "They showed that the critical CTSS category had more lymphopenia and higher IL-6 than non-critical cases." (PMID 35382199, 2022). "Significant among them are neutrophilia, neutrophil-to-lymphocyte ratio (NLR), lymphopenia, inflammatory markers like C-reactive protein (CRP), and cytokines including interleukin-6 (IL-6), interleukin-8 (IL-8), interleukin-18 (IL-18), interferon-α (IFN-α), and tumor necrosis factor (TNF)." (PMID 35464560, 2022). "Moreover, it is often related to alterations in immune activity, including increased levels of pro-inflammatory cytokines (e.g., IL-6 and TNF-α), lymphopenia, and T cell depletion." (PMID 36359845, 2022). "In patients with severe disease, laboratory values taken at primary infection showed signs of lymphopenia and systemic inflammation, including increased concentrations of C-reactive protein (CRP), IL-6, and TNF, and some of these inflammatory markers remained perturbed at 6-month follow-up." (PMID 35078982, 2022). "Severe lymphopenia, C-reactive protein (CRP), D dimers (>1 μg/L), IL-6, ALT, serum ferritin, lactate dehydrogenase, creatine kinase, troponin are markers with high sensitivity, creatinine, prothrombin time, and procalcitonin being associated with higher mortality." (PMID 36428883, 2022). "Also, the majority of patients who died had raised leucocyte count (76.7%), lymphopenia (97.1%), hypoalbuminemia (95.4%), raised LDH (93.6%), raised CRP (98.8%), D-dimer (98.3%), serum ferritin (92.4%) and interleukin 6 level (95.4%)." (PMID 34548976, 2021). "These include: lymphopenia; neutrophilia; neutrophil activation; increased intermediate and non-classical monocytes; high CD64 expression on monocytes and neutrophils; and raised levels of IL-6, IL-18, PAI-1, sCD25, sTNF-R, IP-10, MPO, and PTX3." (PMID 34632327, 2021).
lymphopenia (continued). "Patients with viremia were older (p = 0.006), had poorer baseline oxygenation (PaO2/FiO2; p < 0.001), more severe lymphopenia (p < 0.001) and higher LDH (p < 0.001), IL-6 (p = 0.021), C-reactive protein (CRP; p = 0.022) and procalcitonin (p = 0.002) serum levels." (PMID 34162948, 2021). "High IL-6, CRP, ferritin, and D-dimer levels, as well as lymphopenia, are predictors of fatality." (PMID 33550983, 2021). "Indeed, patients in treatment group, who were less likely to have elevated IL-6 and CRP level and lymphopenia, had a lower occurrence rate of organ dysfunction and better prognosis." (PMID 33746189, 2021). "In addition to IL-6, IL-10, TNF-α and IFNs, other cytokines, chemokines and growth factors were also involved in lymphopenia." (PMID 34578457, 2021). "In addition, the plasma levels of interleukin (IL)-6 and C-reactive proteins (CRP) in severe patients were higher, while lymphocyte counts were reduced, indications of both cytokine storm and lymphopenia." (PMID 33101705, 2020). "In mild cases, this lymphopenia might partly reflect redistribution of lymphocytes to lymphoid organs and tissues, since IFN-I, IL-6, and TNF-α can promote retention of activated lymphocyte in lymphoid organs." (PMID 33335532, 2020). "Both of the cases developed progressive respiratory distress, cardiac dysfunction, and severe coagulation dysfunction after one week of treatment, accompanied by a progressive increase in serum levels of IL-6 and IFN-γ, lymphopenia, hypokalemia, hypoproteinemia, and coagulation dysfunction." (PMID 33232277, 2020). "Additionally, LIP of lymphopenia-insensitive CD4+ T cells requires an intact microflora and is accompanied by the massive accumulation of IL-6 and dendritic cells (DCs)." (PMID 30792713, 2019). "The MIS-C patients who were older (P<0.001) had higher median peak values of CRP (P<0.001), IL-6 (P<0.001), ferritin (P<0.001), procalcitonin (P=0.002), left ventricular systolic dysfunction (P<0.001) and lymphopenia (P=0.01) when compared to those without AKI." (PMID 37954764, 2023). "We, similarly to others, confirmed that leucocytosis, neutrophilia, lymphocytopenia, thrombocytopenia, increased CRP, PCT, ferritin, LDH, D-dimer, and IL-6 levels, as well as impaired oxygenation are suitable indicators for MIS, and might be associated with worse clinical outcomes." (PMID 36830885, 2023). "Several biomarkers predict a poor outcome of the disease, including increased levels of IL-6 (interleukin 6), serum ferritin, CRP (C-reactive protein), LDH (lactate dehydrogenase), D-dimer, and fibrinogen, as well as reduced levels of antithrombin and lymphopenia." (PMID 34395368, 2021). "Interestingly, the elevated IL-10 in the serum was correlated with the appearance of lymphopenia during FMDV infection but not IL-6, IL-2, IL-17, IL-18, IL-1β, TNF-α, IFN-α/β, TGF-β, and CXCL1." (PMID 34960627, 2021). "Lymphopenia is mediated by the overmentioned inflammatory cytokine milieu (especially rich in IL-6, IL-10, and TNF-α), via lymphocyte sequestration into lymphoid tissue and endothelia by IFN-I and TNF-α or by extensive cell death triggered by IL-6 and Fas-FasLigand signaling." (PMID 33996683, 2021). "Besides, a study showed that severe infection by SARS-CoV-2 could create lymphopenia with decreased CD4+ and CD8+, but interestingly, there is no decrease in lymphocytes B. In summary, there is an increase in cytokines IL6, IL2R, IL10, TNFα, and MCP-2 production and a decrease in IFN-γ production." (PMID 34078305, 2021). "From an immunological point of view, the lymphopenia could depend on the possible dysfunctional activation of dendritic cells already mentioned and the high concentration of cytokines such as TNF-α, IL-6, and IL-10, which act as negative regulators of the proliferation and survival of T lymphocytes." (PMID 33324414, 2020).
lymphopenia (continued). "RSV induced a consistent systemic inflammatory response in both waves, characterized by elevated IL-6 and CRP levels, neutrophilia, lymphopenia, and increased neutrophil-to-lymphocyte ratios, with no relevant inter-wave differences." (PMID 42279045, 2026). "Laboratory testing on admission revealed that patients with lymphopenia had higher levels of CRP, IL-6, LDH, and creatinine compared to patients without lymphopenia." (PMID 35160150, 2022). "For example, interleukin-6 (IL-6) can stimulate CD8+ T cell expansion under inflammatory conditions; however, in hospitalized SARS-CoV-2 patients with lymphopenia, IL-6 has been shown to be elevated without an increase in CD8+ T cell counts." (PMID 34260666, 2021). "These patients showed clinical active non-renal manifestations (such as rash, lymphopenia, AIHA, psychosis, and myelitis) and the elevation of either CIC or IL-6." (PMID 29422675, 2018). "Additionally, our data show that IL-6 and CRP were higher in men than women, along with more severe lymphopenia in men, but independent of APLA positivity." (PMID 37626797, 2023). "Indeed, in our study, we found that the WBC, neutrophil, and IG counts, IG percentages, the incidence of leukocytosis, neutrophilia, and lymphopenia, NLR, and IL-6 levels were significantly higher in non-survivors than in survivors." (PMID 36016322, 2022).
schizophrenia (384 papers, 2007 to 2026). A major psychotic disorder characterized by abnormalities in the perception or expression of reality. "Schizophrenia: Higher levels of several inflammatory factors, including interleukin-6 and C-C motif chemokine 28, were associated with an increased risk of schizophrenia, while higher levels of CD40L receptor and other factors were linked to a reduced risk." (PMID 41399369, 2026). "Both ASD and schizophrenia have been associated with elevated levels of pro-inflammatory cytokines such as IL-6, IL-1β, and TNF-α, as well as microglial activation and altered blood–brain barrier permeability." (PMID 40724876, 2025). "Studies show that schizophrenia is associated with elevated levels of pro-inflammatory factors, particularly IL-1β (interleukin 1 beta), IL-6 (interleukin 6), IL-8 (interleukin 8) and TNF-α (tumor necrosis factor alpha-like)." (PMID 39859234, 2025). "For example, IL-6, a cytokine implicated in the aetiology of schizophrenia, is also a key mediator of the characteristic cytokine storm of COVID-19 infection." (PMID 40806558, 2025). "The IL-6/IL-23/Th17 axis has been linked to neuroinflammatory processes and neuropsychiatric conditions, such as schizophrenia, by mediating neuroimmune crosstalk and possibly throwing off the balance of the blood-brain barrier." (PMID 41200225, 2025). "Because inflammatory changes are also implicated in schizophrenia, we performed additional immunohistochemical evaluations of Iba-1 positive microglia as well as ELISA analysis of IL-6 in the same brain regions." (PMID 38363536, 2024). "Studies aimed at this association found NETs and IL-6 to be good predictors and targets in early schizophrenia." (PMID 39816323, 2024). "High levels of IL-6 have been associated with the severity of schizophrenia and the cognitive impairments." (PMID 38627438, 2024). "IL-6 is particularly significant in B cell-related immune activation, with elevated levels often associated with schizophrenia." (PMID 39399496, 2024). "Schizophrenia is associated with elevated levels of IL-6, IL-8, and TNF-α and reductions in the anti-inflammatory IL-10." (PMID 38673018, 2024). "Prenatal exposure to elevated interleukin (IL)-6 levels is associated with increased risk for psychiatric disorders with a putative neurodevelopmental origin, such as schizophrenia (SZ), autism spectrum condition (ASC) and bipolar disorder (BD)." (PMID 36781081, 2023). "A Mendelian randomization study showed that genetically predicted IL-6 levels were associated with brain structure in some regions highly associated with schizophrenia." (PMID 37370004, 2023). "Two other Mendelian randomisation studies also report potentially causal role for IL-6 in schizophrenia." (PMID 37723153, 2023). "On the other hand, schizophrenia has been associated with increased serum levels of cytokines such as IL-1R antagonists, IL-2, IL-6, and acute-phase proteins." (PMID 37875841, 2023). "The existing research about the sex differences in the association of schizophrenia with elevated IL-6 levels or other immune responses is rare, and further study is needed." (PMID 37370004, 2023). "In this study, genetically determined IL-6 was associated with brain structure and potentially affects areas implicated in developmental neuropsychiatric disorders, including schizophrenia and autism." (PMID 35353173, 2022). "The severity of CFS-like symptoms in schizophrenia is associated not only with increased IL-6 but also IL-10 levels." (PMID 35330475, 2022). "For instance, associations between IL-6 and a history of childhood maltreatment have only been investigated in four studies among patients with schizophrenia or psychosis." (PMID 36572669, 2022). "IL-6 has been widely studied in different aspects of schizophrenia (its onset, progression, association with different clusters of symptoms)." (PMID 35873262, 2022).
schizophrenia (continued). "It is worth noting that in schizophrenia, activation of the pathogenic IL-6/IL-23/Th17 axis is linked to other important pathways." (PMID 36256663, 2022). "The aim of the study was to search for associations between BDNF, CRP, IL-6 and clinical symptoms, cognitive and personal performance in patients with paranoid schizophrenia." (PMID 35873262, 2022). "The severity of CFS-like symptoms in schizophrenia, another neuroimmune disorder, is associated with immune–inflammatory markers, including increased plasma IL-6." (PMID 35330475, 2022). "It is also important to note that after considering the detrimental effects of the IL-6/IL-23/Th17 axis on the phenome of schizophrenia, IL-10 showed an inverse association with the phenome." (PMID 36256663, 2022). "The overexpression of IL-6 has been linked to the onset of neurodevelopmental and neurodegenerative diseases and mental disorders such as schizophrenia and autism." (PMID 33078273, 2021). "Controlling for potential confounders (age, sex and body mass index), having a diagnosis of schizophrenia remained significantly associated with increased hsCRP and IL-6." (PMID 34465310, 2021). "In line with this evidence and results from previous MR studies, we report evidence for a potential causal role of IL-6 in schizophrenia, in both univariable MR and MVMR analyses." (PMID 34280516, 2021). "Other studies have demonstrated that aberrations in parvalbumin interneurons are implicated in schizophrenia and that elevated IL-6 levels in CNS disrupt working memory." (PMID 33746786, 2021). "Several studies have reported an association between the −174G/C polymorphism in the IL-6 gene and schizophrenia that influences disease risk." (PMID 33746786, 2021). "An association between treatment-resistant schizophrenia and an elevated level of IL-6 has been described and between the IL-6 level and illness duration." (PMID 33746786, 2021). "In patients with schizophrenia, presence of gene polymorphisms of proinflammatory cytokines, such as IL-1β and IL-6, have been linked to high serum levels of these cytokines." (PMID 33746786, 2021). "The CRP-schizophrenia association attenuated completely after taking into account IL-6 and sIL-2Rα in MVMR (OR=1.02; 95% C.I., 0.81-1.28)." (PMID 34280516, 2021). "Interleukin 6 (IL-6) has been described as a key molecular mediator for the early pathophysiological mechanisms that predispose to neuropsychiatric disorders such as schizophrenia and autism." (PMID 33868085, 2021). "Our results indicate some evidence for a potential causal role of a number of immunological proteins/traits in schizophrenia including IL-6, sIL-2Rα, IL-9, MCP-1 and BDNF." (PMID 34280516, 2021). "We extended this association to show that the SIRT1 interacting with IL-6 as the influencing factor for the MetS in schizophrenia patients." (PMID 33324265, 2020). "In adult neurons, an increased IL-6 level has been associated with the dysfunction of GABAergic parvalbumin-containing inhibitory neurons leading to schizophrenia-like behavioural disturbances." (PMID 32664639, 2020). "Due to these microglial functions, authors pointed out that IL-6 was associated with KYNA production by increasing this metabolite in patients with schizophrenia." (PMID 32061259, 2020). "One study on Polish schizophrenia patients detected a functional polymorphism in the proinflammatory cytokine IL-6 and the anti-inflammatory cytokine IL-10 genes in patients with paranoid schizophrenia." (PMID 31405205, 2019). "Whereas they included a comprehensive array of metabolic markers and CRP, future studies should consider including other inflammatory markers, e.g. IL-6 and other cytokines, that have been consistently linked with schizophrenia risk in observational studies." (PMID 31563954, 2019). "In primary cortical neuronal cultures from rats, IL-6-induction significantly reduced the complexity of neuronal dendritic arborization, an effect that was linked to risk for schizophrenia." (PMID 31071949, 2019).